MMP3 (matrix metallopeptidase 3)
Diseases named in the same sentence as MMP3 in open-access papers (continued):
Sharing a sentence is not in itself a finding about the gene and the disease.
atherosclerosis (continued). "MMP-3 (or stromelysin-1) is an enzyme involved in the breakdown of extracellular matrix proteins and tissue remodeling in physiological (e.g., embryogenesis) and pathophysiological (e.g., tumor metastasis and atherosclerosis) processes." (PMID 32831121, 2020). "The initial incubation of cultures of primary human cells relevant to atherosclerosis with equimolar concentrations of each IL-1 isoform, and the examination of MMP-3 mRNA expression, protein secretion, and activity helped to assess rigorously the potential functional overlap of IL-1α and IL-1β." (PMID 27032103, 2016). "This study investigated whether IL-1α and IL-1β overlap in regulating the expression of MMP-3 and other remodeling-related proteases in isolated human cells relevant to atherosclerosis in primary culture and in fresh human carotid endarterectomy specimens." (PMID 27032103, 2016). "Thus, an insight into the molecular mechanisms that govern the regulation of MMP3 expression will enhance our understanding of the pathogenesis of atherosclerosis and plaque rupture." (PMID 20360864, 2010). "Acting as an upstream activator, MMP-3 enhances tissue degradation processes, a mechanism especially significant in chronic inflammatory diseases, where uncontrolled tissue remodeling can result in excessive connective tissue breakdown, as observed in AS and atherosclerosis." (PMID 40277922, 2025). "Previous studies have shown that high doses of crocin proportionally reduce the levels of macrophages and their inflammatory derivatives in atherosclerosis, including MCP-1, TNF-α, IL-6, MMP-2, MMP-3, and MMP-9." (PMID 38830933, 2024). "In the lipid and atherosclerosis pathway, lncRNA AC001611.2 expression correlated positively with four genes (MMP3, MMP9, IL-1 and CXCL3) whereas six other lncRNAs correlated negatively with the same genes." (PMID 35224318, 2022). "In the present study, we found that MMP3 and MMP9 secretion by platelets participates in atherosclerosis." (PMID 33728029, 2021). "The level of MMP-12, which can hydrolyze elastin and intercellular matrix proteins, as well as activating MMP-3 and MMP-2, was statistically significantly higher in the group of men with atherosclerosis—2.1 times compared to the control group." (PMID 34205079, 2021). "mRNA expression of the two proximal genes, MMP3 and MMP12 was analysed from 29 carotid, 15 abdominal aorta, 24 femoral plaques, and 28 atherosclerosis free left internal thoracic artery controls." (PMID 25078452, 2014). "Similarly, in atherosclerosis, TLR activation in endothelial cells and macrophages within atherosclerotic plaques induces MMP-3 expression, contributing to inflammation progression and plaque instability." (PMID 40277922, 2025). "IL-1β, a therapeutic target in atherosclerosis and other cardiovascular diseases, signals through JNK and NF-κB and inhibition of IL-1β may decrease the production of MMP3, SMC chemotaxis, and inflammasome-mediated inflammation." (PMID 36233314, 2022). "Metalloproteinases are all suggested to be markers of vulnerable plaques and in this study the biomarker of influence in separating those with and without progression of the atherosclerosis in a subgroup of the patients with RA was a metalloproteinase, MMP3." (PMID 31381601, 2019). "To determine whether liquefaction of the brain following stroke shares other characteristics with atherosclerosis we measured the levels of OPN, IL-18, MMP-2, MMP-3, and MMP-8." (PMID 30417081, 2018). "Indeed, our findings support that atherosclerosis development is accompanied by an increase in MMP-2, MMP-3, MMP-8, MMP-9, TIMP-1 and TIMP-2 levels." (PMID 25264981, 2014). "FLI1 regulates the expression of metalloproteases (MMP-1, MMP-3, and MMP-10) and the pro-inflammatory cytokine IL-10; therefore, during chronic inflammatory conditions, such as AR and atherosclerosis, FLI1 down-regulation could attenuate tissue damage associated with inflammatory responses." (PMID 39767648, 2024).
atherosclerosis (continued). "Furthermore, our results showing the correlations between MMP-3, -9, their ratios with TIMP-1 and blood pressure as well as endothelial-dependent response could be beneficial for the prevention of obesity-related cardiovascular diseases such as hypertension or atherosclerosis." (PMID 34625635, 2021). "However, our results showed no significant change in MMP-3 levels in CAD patients, indicating that further research is needed to clarify MMP-3’s role in atherosclerosis." (PMID 39445733, 2025).
lung carcinoma (39 papers, 2007 to 2025). "At the same time, in lung cancer cells, MMP3 increases the activity of MMP9, causing the invasion of cancer cells in vitro and in vivo." (PMID 36114508, 2022). "For instance, in lung cancer, IL-6 regulates the expression of MMP-3 through ATM phosphorylation, a potential factor associated with drug resistance in this cancer type." (PMID 33392094, 2020). "The main aim of this study was to investigate the relationship between 3 functional polymorphisms in the regulatory regions of the human gelatinases MMP2 and MMP9 and the human stromelysin MMP3 and lung cancer risk in the individuals from the CAPUA study." (PMID 22455335, 2012). "We evaluated the effect of three polymorphisms in the promoter regions of two human gelatinases, MMP2 and MMP9, and the human stromelysin MMP3 on the risk and survival time of lung cancer." (PMID 22455335, 2012). "MMP3 is associated with poor survival in various cancers, and its polymorphism might increase the risk of lung cancer." (PMID 32411535, 2020). "In this sense, the overexpression of MMP2, MMP9 and MMP3 has been detected in various types of human cancer, such oesophageal cancer, gastric carcinoma, ovarian and lung cancer, and has been significantly associated with tumour progression and decreased survival." (PMID 22455335, 2012). "For example, MMP3 is highly expressed in adipocyte-derived exosomes in obese lung cancer patients, which is usually transferred to lung cancer cells." (PMID 36291860, 2022). "As a result, MMP3 promotes the activity of MMP9 in lung cancer cells, thus mediating cancer cell invasion in vitro and in vivo." (PMID 36291860, 2022). "Nontumor exosomes derived from adipocytes increase the activity of MMP9 by delivering MMP3 to lung cancer cells, thereby promoting the invasion and migration of lung cancer cells." (PMID 34511114, 2021). "Increased expression of MMP-3 and MMP-13 are associated with the augmentation of cell migration in lung cancer." (PMID 32711573, 2020). "MMP3 mRNA expression was higher in head and neck cancer, stomach cancer, cervical cancer, pancreatic cancer, colorectal cancer, lung cancer, and urothelial cancer, compared to the ovarian, testis and other cancer types." (PMID 32260433, 2020). "MMP3 increases the activity of MMP9 in lung cancer cells and facilitates the invasion of cells in vitro and in vivo." (PMID 31500658, 2019). "Mechanistically, adipocyte-derived exosomes increase MMP3, and MMP3 is transferred to lung cancer cells." (PMID 31500658, 2019). "In lung cancer, MMP-3 elicited the expression of Rac1B, which subsequently stimulated the expression of transcription factor Snail to induce EMT." (PMID 30545369, 2018). "Compared with 3T3-L1 cells, 3T3-L1 adipocytes are enriched in MMP3 protein and can transfer MMP3 to 3LL lung cancer cells." (PMID 29137230, 2017). "In support of these findings, recent clinical studies have demonstrated a close correlation between MMP-3 expression and the development of lung metastases in breast and lung cancers." (PMID 27562075, 2016). "As MMP-3/MMP-13 plays the pivotal roles in TNF-α increased metastasis, we therefore investigated the role of MMP-3/MMP-13 in IL-6 enhanced lung cancer metastasis." (PMID 26528698, 2015). "Patient breast and lung cancer tissue biospecimens revealed epithelial staining patterns for MMP3, similar to pancreatic carcinoma TMAs." (PMID 26807201, 2015). "We also find that MMP3 gene expression can serve as a prognostic marker for patient survival in breast and lung cancer." (PMID 26807201, 2015). "Pancreatic adenocarcinoma tissue microarrays (TMAs) were stained for MMP3, Rac1b (a tumorigenic splice isoform of Rac1 previously shown to be upregulated by MMP3 in pancreas, breast, and lung cancers), collagen I, and H&E." (PMID 26807201, 2015). "In the present study, our results reveal that IL-6 inducing ATM phosphorylation increases lung cancer metastasis via up-regulation of MMP-3/MMP-13." (PMID 26528698, 2015).
lung carcinoma (continued). "Here, we investigated the role of ATM phosphorylation in IL-6 increasing MMP-3/MMP-13 expression, but the exact mechanism by which MMP-3/MMP-13 promoting lung cancer metastasis is still to be clarified." (PMID 26528698, 2015). "Most importantly, the in vivo test showed that the inhibition of ATM abrogate the effect of IL-6 on lung cancer metastasis via MMP-3/MMP-13 down-regulation." (PMID 26528698, 2015). "We have investigated the association between the -735 C/T, the -1171 5A/6A, and the -1562 C/T polymorphisms in the MMP2, MMP3 and MMP9 genes, respectively, and the risk and survival of lung cancer." (PMID 22455335, 2012). "Similarly, exosmal miR‐494 and miR‐542‐3p from pulmonary interstitial cells down‐regulate the expression of cadherin‐17, thus increasing the expression level of matrix metalloproteinase MMP2 and MMP3 and promoting the distant metastasis of lung cancer cells." (PMID 39548655, 2024). "Interestingly, our analysis also found that lung cancer cell lines with higher OXPHOS (MMP3 and MMP12) and CAC (MMP5) were more sensitive to elesclomol, consistent with previous study, supporting the reliance of our analysis results." (PMID 39393173, 2024). "IR inhibited the proliferation, migration and invasive ability of CAFs in lung cancer, which might be related to the power of IR to promote MMP-3, inhibit MMP-1, and enhance integrins α2, β1 and α5 to stabilise lesion exposure." (PMID 38173726, 2023). "In this study we show that MMP3 and its downstream effector Rac1b are both strongly expressed specifically in tumor cells in pancreatic, breast, and lung carcinomas, and that tumor expression of MMP3 is correlated with poor patient survival and earlier recurrence in all of these cancers." (PMID 26807201, 2015). "With regard to the MMP3 -1171 5A/6A polymorphism, two studies have investigated the association between this polymorphism and lung cancer risk, showing a non-statistically significant association." (PMID 22455335, 2012). "Thus, adipocyte-derived exosomes increase the MMP3 expression in lung cancer cells." (PMID 36114508, 2022). "An acidic microenvironment induces MMP2, MMP3, MMP9 and MMP13 expression to promote breast or lung cancer progression." (PMID 35414794, 2022). "In the C2 cluster, matrix metallopeptidase 3 (MMP3), which has been reported to promote the epithelial-mesenchymal transition of lung cancer 57, was inhibited by digoxin." (PMID 34646392, 2021). "We concentrated on those genes that revealed a differential expression between IPF and lung cancer, such as higher expression of MMP1 and MMP3 in IPF than ADC, and lower expression of COL4A1 in IPF than in ADC." (PMID 33905434, 2021). "High expression of MMP3 and CCN2/CTGF were prognostically unfavorable in lung cancer and head and neck cancer." (PMID 32260433, 2020). "MMP-3 has been revealed to remodel ECM and has a close correlation with the progression of breast, gastric and lung cancer." (PMID 26528698, 2015). "The present study demonstrated that high IL-6 level increases both expressions and activities of MMP-3 and MMP-13, hence augments cell migration abilities of lung cancer." (PMID 26528698, 2015). "In the present study, we found that the high IL-6 level reveals both the increased expression of MMP-3/MMP-13 and the enhanced migration abilities of lung cancer cells." (PMID 26528698, 2015). "But until now, little is known about the roles of MMP-3 and MMP-13 in IL-6 correlated lung cancer metastasis." (PMID 26528698, 2015). "Then, the inhibition of ATM phosphorylation abolishes IL-6 increased expression of MMP-3/MMP-13, hence abrogates IL-6 correlated lung cancer metastasis both in vitro and in vivo." (PMID 26528698, 2015). "Together, these data demonstrate that MMP-3 and MMP-13 are the key MMPs in IL-6 promoting lung cancer metastasis." (PMID 26528698, 2015). "MMP-3 has a protective role in squamous cell carcinoma and macrophage MMP-12 is an anti-target in lung carcinoma." (PMID 17375198, 2007).
lung carcinoma (continued). "Compared with normal lung tissues, the expression of MMP3, MMP9, and PPARG was increased in lung cancer tissues, and the expression of ALOX5 and ICAM1 was decreased in lung cancer tissues, which was basically consistent with the analysis results in the GEPIA database." (PMID 39440769, 2025). "Expression of MMP1 (collagenase), MMP2 (gelatinase), and MMP3 (stromelysin) transcripts was not significantly altered in lung cancer cells co-cultured with MSCs, but all three transcripts were downregulated in MSCs after co-culture with lung cancer cells." (PMID 33119681, 2020). "As EMT could be affected by the composition and structure of ECM, the findings that ATM phosphorylation increases MMP-3/MMP-13 expression and promotes lung cancer metastasis indicate that the phosphorylation of ATM might be involved in IL-6 promoting EMT." (PMID 26528698, 2015). "All together, these data suggest that ATM could be activated by the treatment with IL-6, hence increases the expression of MMP-3/MMP-13 and promotes lung cancer metastasis." (PMID 26528698, 2015). "Moreover, the inhibition of ATM phosphorylation not only abrogates IL-6 increased, MMP-3/MMP-13 mediated cell migration in vitro, but also suppresses IL-6 correlating lung cancer metastasis in vivo." (PMID 26528698, 2015). "Pleural fluid marker analysis revealed highly significant differences in the levels of seven of the analysed markers between benign and lung cancer patients: the concentrations of all seven markers, MMP-9, MMP-3, CycD1, Ki67, ImAnOx, carbonyls and p27, were lower in cancer patients by 9–65%." (PMID 20216542, 2010). "To further verify the role of NDUFA4 in the growth and metastasis of lung cancer cells, we detected the expression of cell-growth-related molecules including CDK2, CDK3, CDK4, and CDK6, as well as metastasis-related molecules including CXCR4, E-Cadherin, MMP2, MMP3, and MMP9, respectively." (PMID 28325285, 2017). "In addition, increased MMP3 protein levels and MMP9 activities are noted in tumor tissues from obese lung cancer patients, which may also result from exosome-mediating protein transfer." (PMID 29137230, 2017). "Additionally, the inhibition of MMP-3 or MMP-9 could achieve similar results in NCI-H446 and A549 cells, confirming the crucial role of MMPs in TNF-α promoting lung cancer cell migration." (PMID 27556690, 2016). "All these findings demonstrate that IL-6 inducing ATM activation increases the expression of MMP-3/MMP-13, augments the abilities of cell migration and promotes lung cancer metastasis, indicating that ATM is a potential target molecule to overcome IL-6 correlated lung cancer metastasis." (PMID 26528698, 2015). "MMPs, such as MMP-3, MMP-9, MMP-13 were negative prognostic factors for lung cancer survival." (PMID 27556690, 2016).
colorectal cancer (35 papers, 2006 to 2025). A primary or metastatic malignant neoplasm that affects the colon or rectum. "This study also underscores the significant diagnostic capabilities of MMP10 and MMP3 in colorectal cancer." (PMID 40595862, 2025). "The downregulated migration activity was revealed to be linked with the inactivation of Janus kinase/STAT3/matrix metalloproteinase 3 (JAK2/STAT3/MMP3) pathway in human colorectal cancer HCT-116 cells." (PMID 30380774, 2018). "In different study populations higher circulating levels of MMP-1, MMP-2 and MMP-3 were strongly associated with all-cause mortality in patients with colorectal cancer, myocardial infarction or heart failure." (PMID 28446168, 2017). "Matrix-metalloproteinase-3 (MMP3) is highly expressed in colorectal carcinomas, the encoded protein plays role in tumor invasion, lymph node involvement and metastatic spread." (PMID 26208990, 2015). "To explore whether the alteration of Mmp3 expression plays a critical role in HDAC11- mediated inhibition of colorectal cancer cell migration and invasion, we designed vectors encoding mouse Mmp3 and reintroduced it into CT26.WT cells." (PMID 35399729, 2022). "Alternatively, the inverse relationship between IPC and the high-expressing MMP-1 2G/2G genotype may reflect linkage disequilibrium between the MMP-1 2G and MMP-3 6A alleles as has been reported in colorectal cancer." (PMID 17922906, 2007). "In our experimental conditions, blueberry pomace extract most effectively inhibited MMP-1, MMP-2, and MMP-3 in C2BBe1 colorectal cancer cells." (PMID 39200479, 2024). "They found that HDAC11, which downregulates MMP-3, was underexpressed in patients with colorectal cancer." (PMID 37955015, 2023). "It was found that the expression of the MMP3 gene decreases in stage IV of colorectal cancer compared to other stages (P value < 0.01)." (PMID 37940644, 2023). "We also found HDAC11 inhibits the migration and invasion of colorectal cancer cell by downregulating Mmp3 expression." (PMID 35399729, 2022). "MMP-3 and MMP-13 is upregulated in human colorectal carcinomas, and MMP-13 activity is associated with poor prognosis in colorectal cancer." (PMID 28505114, 2017). "We have validated that integrinβ6 promoted the invasion, metastasis and degradation of extracellular matrix of colorectal cancer, thyroid carcinoma, gastric carcinoma, and pancreatic carcinoma through up-regulation of MMP-3/MMP-9." (PMID 27835891, 2016). "We investigated the role of MMP1, MMP3 and MMP7 promoter polymorphisms as colorectal cancer risk factors in a case-control study of cases with large adenomatous polyps (n = 295), versus small adenomatous polyps cases (n = 302) or PF controls (n = 568)." (PMID 17125518, 2006). "Additionally, we find a novel mechanism that HDAC11 inhibits colorectal cancer cell migration and invasion by down-regulating Mmp3 expression in vitro." (PMID 35399729, 2022). "Furthermore, we recapitulated the gene expression levels of Mmp3, Mmp10, and Mmp13 from large cohorts of ulcerative colitis (UC) and colorectal cancer (CRC) patients that are available from the GEO database (GSE38713 and GSE37364)." (PMID 25742789, 2015). "The increased MMP-3 activity in colorectal cancer suggests that this enzyme might play a role in the progression of the disease." (PMID 23108733, 2013). "Both KAE and cisplatin led to extensive reduction in the levels of Autotaxin, Carbonic Anhydrase IX, cathepsins, MMP-3, u-Plasminogen Activator/Urokinase, and HMOX1 in colorectal carcinoma cultures." (PMID 41515404, 2025).